FOXM1 (forkhead box M1)
Diseases named in the same sentence as FOXM1 in open-access papers (continued):
Sharing a sentence is not in itself a finding about the gene and the disease.
breast cancer (continued). "In the breast cancer tissues, the strongest correlations were reported between FOXM1/ZNF337.AS1 and FOXM1/RAMP2.AS1 pairs." (PMID 34094972, 2021). "Consistently, panepoxydone inhibits NFkB and FOXM1 and exhibits a strong anti-tumor activity against breast cancer cell lines including ER+/HER2− MCF7 cells, underlining the relevance of NFkB and FOXM1 as targets in ER+/HER2− breast cancer." (PMID 33920089, 2021). "Several earlier publications have noted the involvement of FOXM1 in inflammation in keratinocytes and in other types of cancer, and resistance to endocrine therapies in breast cancer has been shown to result in the upregulation of interferon signaling." (PMID 34944900, 2021). "Consistently, knockdown of FOXM1 in breast cancer cells can restore sensitivity to endocrine therapies." (PMID 33920089, 2021). "Similar results were found using an alternative cellular model, the MCF-7 breast cancer epithelial cell line, in which FOXM1 repression also induces BMF upregulation." (PMID 34035233, 2021). "We have identified small molecule inhibitors of FOXM1 that suppress the activity of this protein and reduce the level of FOXM1 in breast cancer cells and tumors." (PMID 34944900, 2021). "The positive feedback signaling loop between AURKA and FOXM1 is crucial for breast cancer stem cell self-renewal." (PMID 33451333, 2021). "The identified ACSS1 is experimentally validated to promote epithelial-to-mesenchymal transition of bladder cancer cells, and the predicted FOXM1-targets interactions are verified and are predictive of relapse in breast cancer." (PMID 33667222, 2021). "They worked with 21T cells and found that miR-671-5p was decreased during breast cancer progression, contrary to FOXM1." (PMID 34804940, 2021). "The identified ACSS1 in bladder cancer and predicted FOXM1-targets interactions in breast cancer are both validated." (PMID 33667222, 2021). "A strong positive correlation between HER2 overexpression and FOXM1 has been reported in breast cancer cell lines and in breast cancer samples with HER2 amplification." (PMID 33920089, 2021). "FOXM1 overexpressing breast cancer cells displayed an anti-apoptotic phenotype due to up-regulated expression of XIAP and BIRC5 anti-apoptotic genes." (PMID 33431968, 2021). "Concerning the HR repair pathway, FOXM1 upregulates the expression of NBS1 in human breast cancer cells." (PMID 34680943, 2021). "We also found evidence that RNF168, an E3 ubiquitin ligase able to ubiquitinate FOXM1 in breast cancer, displays nuclear localisation." (PMID 33981003, 2021). "Elevated interferon signaling and STAT1 and active pSTAT1 and HER2 expression in ER-positive FOXM1 inhibitor-resistant breast cancer would likely provide an immune suppressive environment that would allow the cancer to progress." (PMID 34944900, 2021). "Another study shows that circular RNA circTP63 enhances estrogen receptor-positive breast cancer progression and malignant behaviors through the miR-873-3p/FOXM1 axis." (PMID 34789260, 2021). "The drug with the lowest (best) IC50 was Thiostrepton (IC50 = 3.95 ± 0.02 x 10−6 M), a cyclic oligopeptide used as a topical antibiotic in animals that interacts with the transcription factor FOXM1 to inhibit the growth of breast cancer cells in vitro." (PMID 34194331, 2021). "A comprehensive genomic analysis of breast cancer cells previously identified the transcription factors, FOXM1 and c-myc, which are hyperactivated in TNBCs as factors to contribute to the downregulation of the CD95 expression." (PMID 34917906, 2021). "We and others have reported that proteasome inhibitors (PIs) inhibit the expression of FOXM1 in breast cancer and other types of cancer." (PMID 33920089, 2021).
breast cancer (continued). "FOXM1 has also been shown to promote taxane resistance in breast cancer, gastric cancer, hepatocellular carcinoma, prostate cancer, and nasopharyngeal carcinoma." (PMID 34205406, 2021). "We used small molecule inhibitors of FOXM1 to understand how they impact gene regulatory networks in suppressing cancer cell survival and the rewiring of gene networks that occurs when breast cancer cells become resistant to these compounds." (PMID 34944900, 2021). "The forkhead box protein 1 (FOXM1) is a transcriptional activator that regulates ERα expression in normal breast tissues, as well as during ERα+ breast cancer initiation, progression and drug resistance." (PMID 34831091, 2021). "FOXM1 and PR are considered to be ERα-target genes that are expressed under the influence of estrogen as long as breast cancer cells are estrogen-responsive." (PMID 33920089, 2021). "In human breast cancer tissues, FOXM1 protein expression level is highly correlated with that of SIRT1." (PMID 34680943, 2021). "FOXM1 is upregulated in several solid tumours, including breast cancer, and is also correlated with a poor outcome of patients." (PMID 34206484, 2021). "FOXM1 fosters the outgrowth of ER+ breast cancer cells and circumvents drug-induced senescence in the presence of endocrine therapies." (PMID 33920089, 2021). "In breast cancer, FOXM1 was found to promote the activity of YAP1 and maintain the cancer cell stemness." (PMID 33959615, 2021). "Improved understanding of how FOXM1 inhibitors suppress breast cancer and how cancer cells can defeat their effectiveness and acquire resistance should be helpful in directing further studies to move these agents towards translation into the clinic." (PMID 34944900, 2021). "ZMYND8 depletion not only enhances Polycomb-dependent function of EZH2 in hypoxia-exposed breast cancer cells or von Hippel–Lindau (VHL)-deficient ccRCC cells, but also suppresses the FOXM1 transcription program." (PMID 33593912, 2021). "For example, HMGA1 can promote breast cancer angiogenesis via supporting the transcriptional activity of FOXM1." (PMID 33407473, 2021). "In triple-negative breast cancer (TNBC) cells, the proto-oncogene transcription factor forkhead box M1 (FOXM1) can regulate eEF2K and affect breast cancer cell migration and invasion, progression, and tumorigenesis." (PMID 33673713, 2021). "Consistent with its role in tumor progression, overexpression of FOXM1 has been shown to correlate with a poor prognosis in many cancer patients, including breast cancer." (PMID 32858881, 2020). "While confirming that eIF4E can govern the protein synthesis of ERα and FOXM1, in ER+ breast cancer, FOXM1 is a critical ERα target gene for modulating tamoxifen response." (PMID 32066877, 2020). "To gain insight into how the FOXO3a/FOXM1 axis regulates stem-like properties of breast cancer cells, we first examined the expression of five stemness-related genes after overexpressing FOXO3a or downregulating FOXO3a in MCF-7 and T47D cells." (PMID 31296961, 2020). "Clinically, we observed a significant inverse correlation between FOXO3a and FOXM1/SOX2/DNMT1 expression levels, and loss of FOXO3a expression or increased expression of FOXM1, SOX2, and DNMT1 predicted poor prognosis in breast cancer." (PMID 31296961, 2020). "These compounds suppress the activity of the cell cycle regulator FOXM1, which is overexpressed in many breast cancers, and in a variety of other cancers, including ovarian, pancreatic, lung, colon, and glioblastoma." (PMID 32961773, 2020). "Previous reports have demonstrated that FOXM1 is oncogenic, in breast cancer, hepatocellular carcinoma, prostate cancer, lung cancer, and colorectal cancer, and plays important roles in angiogenesis, invasion, and metastasis." (PMID 33299863, 2020). "ALKBH5 enhances self-renewal and oncogenesis of glioblastoma by sustaining FOXM1 expression, and it also mediates the hypoxia-induced stem cell phenotypes of breast cancer." (PMID 32772918, 2020).
breast cancer (continued). "We further investigated the clinical significance of DNMT1/FOXO3a/FOXM1/SOX2 signaling in breast cancer." (PMID 31296961, 2020). "More interestingly, OTUB1 was shown to promote deubiquitination of FOXM1 in breast cancer and ovarian cancer to facilitate tumor progression." (PMID 32257108, 2020). "Taken together, these data showed that inhibition of DNMT activity suppresses tumor growth via regulating FOXO3a/FOXM1/SOX2 signaling in breast cancer." (PMID 31296961, 2020). "Elevated expression of FOXM1 predicts poor survival in ER+ and progesterone receptor-positive breast cancer and in patients treated with adjuvant chemotherapy or tamoxifen." (PMID 32976773, 2020). "Another study found miR-671-5p expression was significantly decreased in breast cancer via down-regulation of forkhead box protein M1 FOXM1 expression, an oncogene transcription factor." (PMID 31972983, 2020). "In drug-sensitive cells of breast cancer, FOXM1 is downregulated by chemotherapy, but in the resistant cells, FOXM1 maintains its levels." (PMID 32679860, 2020). "Our study uncovers a novel mechanism whereby phosphorylation independent eIF4E translational reprogramming in governing the protein synthesis of ERα and FOXM1 contributes to anti-estrogen insensitivity in ER+ breast cancer." (PMID 32066877, 2020). "In breast cancer, the forkhead box protein M1 (FoxM1) has tumor-promoting functions impacting patient prognosis." (PMID 32042016, 2020). "Knockdown of FOXM1 in ERα+ MCF7 breast cancer cells led to reduced expression of ERα, cell cycle arrest, and senescence, partially phenocopying the effects of ectopic RASSF1A expression in these cells." (PMID 32967092, 2020). "Several studies have demonstrated that FOXM1 promotes malignant progression by activating the expression of cell cycle genes in various cancers such as liver cancer, breast cancer, and ovarian cancer." (PMID 33124191, 2020). "On the other hand, the thiazole antibiotic, thiostrepton, was found to induce cell cycle arrest and apoptosis in breast cancer cells by depletion of FOXM1." (PMID 32961773, 2020). "According to the molecular mechanism proposed in this study, developing novel drugs that target FOXM1 is expected to be effective for various types of cancers, including breast cancer." (PMID 32858881, 2020). "In our study, we found that the expression of FoxM1 also correlated with worse RFS in breast cancer patients." (PMID 32042016, 2020). "Studies in breast cancer cells MDAMB 231 have also shown FOXM1 to modulate proliferation, clonal expansion, migration and stemness in YAP1 dependent manner." (PMID 33680951, 2020). "Using the METABRIC dataset, we showed that increased FOXM1 expression correlates with poorer survival in PIK3CA mutant breast cancer patients and that survival is decreased in ER+ breast cancer patients with FOXM1 copy number gain." (PMID 32976773, 2020). "It has been shown that FOXM1 nuclear positivity is well correlated with HER2 expression in breast cancer patients." (PMID 33680951, 2020). "The expression of XIAP in breast cancer cells is regulated by FOXM1 which acts as an intermediate between XIAP and OGT52,53." (PMID 32994395, 2020). "Together, these results suggested that the regulation of CSC properties by the FOXO3a/FOXM1 axis is mediated by SOX2 in breast cancer cells." (PMID 31296961, 2020). "FOXM1 expression was determined by immunohistochemical analysis of biopsies obtained from three patients with advanced breast cancer enrolled in the POSEIDON phase Ib trial, which was designed to assess the efficacy of treatment with GDC-0032 plus tamoxifen." (PMID 32976773, 2020). "In eIF4E overexpressing breast cancer, the increased ERα protein expression in turn enhances FOXM1 transcription, which together with its increased translation regulated by eIF4E, contributes to tamoxifen resistance." (PMID 32066877, 2020).
breast cancer (continued). "Our previous work delineated a role for these FOXM1 inhibitory compounds in eliciting a G2/M block in the cell cycle and inducing apoptosis in breast cancer cells." (PMID 32961773, 2020). "Consistent with our polysome fractionation experiments which show that eIF4E modulated protein synthesis of both ERα and FOXM1, the correlation between eIF4E with ERα and FOXM1 was verified in vivo using 134 Chinese breast cancer samples." (PMID 32066877, 2020). "We show here that persistent FOXM1 expression following drug treatment is a biomarker of resistance to PI3Kα inhibition in ER+ breast cancer." (PMID 32976773, 2020). "Inhibition of DNMT activity suppressed tumor growth via regulation of FOXO3a/FOXM1/SOX2 signaling in breast cancer." (PMID 31296961, 2020). "FOXM1 has been shown to regulate cell cycle during progression of prostate cancer, breast cancer, colorectal cancer and RCC." (PMID 32257108, 2020). "In particular, recent studies have revealed that FOXM1 is tightly linked with estrogen receptor (ERα) activity and HER2 protein status in breast cancer." (PMID 32858881, 2020). "FOXM1 is an ERα transcriptional target that mediates its mitogenic functions and has been shown to play a role in breast cancer endocrine sensitivity and resistance." (PMID 32976773, 2020). "Knockdown of YAP1 in ERα+ MCF7 breast cancer cells led to reduced expression of ERα and FOXM1, cell cycle arrest, and senescence and inhibition of AKT1 and increased activity of FOXO3A." (PMID 32967092, 2020). "Epirubicin treated, MCF-7 breast cancer cells have shown induction of FOXM1 expression through P38MAPK–E2F1 axis." (PMID 33680951, 2020). "Intriguingly, FOXM1 was predicted to regulate cell type-specific genes including ESR1 in the ER+ breast cancer cell line MCF-7 by directly binding to cis-regulatory elements that include the canonical FKH motif." (PMID 32858881, 2020). "We found that, in general, adjacent normal tissues exhibited relatively high FOXO3a expression and very low expression of FOXM1, SOX2, and DNMT1; in contrast, breast cancer tissues had low FOXO3a, but high FOXM1, SOX2, and DNMT1 expression." (PMID 31296961, 2020). "The transcription factor FOXM1 is overexpressed in breast cancers of all subtypes, but is especially high in TNBC, as well as in many other types of cancers, including ovarian, pancreatic, prostate, and glioblastoma." (PMID 32961773, 2020). "Foxm1 has been found overexpressed in a variety of solid tumors, including breast cancer and indeed, we also observed a 9-fold increase in 4T1 cells." (PMID 32793490, 2020). "FOXM1 can physiologically regulate ERα in breast carcinoma cells through activating transcription of the ERα promoter, thereby increasing ERα expression." (PMID 32967092, 2020). "The family member, FOX subclass M1 (FOXM1), is highly expressed in various types of human malignancies, including breast cancer." (PMID 30927552, 2019). "CDCA8 was often studied in bladder cancer and breast cancer, CDCA8 and FOXM1 appeared to be related in breast cancer." (PMID 31139013, 2019). "It induces apoptosis through both extrinsic death receptor and mitochondrial death pathways in human breast cancer MDA-MB-231 cells, and inhibits cell proliferation and induces pro-apoptosis in human breast cancer MCF-7 cells by FoxM1 inhibition." (PMID 31719837, 2019). "FOXM1 is a member of the forkhead box (Fox) transcription factor family, which is known as an oncogene involved in breast cancer, cervix cancer, prostate cancer, and so on." (PMID 31708970, 2019). "There is a significant positive correlation between Aurora‐A and FOXM1 in breast cancer (r = .53, P < .01)." (PMID 31359594, 2019). "PMLIV overexpression represses the proliferation and self‐renewal of breast cancer cells and downregulates FOXM1 expression and protein activity." (PMID 30927552, 2019).
breast cancer (continued). "Other literature shows platelet-derived growth factor subunit a (PDGFA) is a transcription target of FoxM1, and FoxM1 promotes breast cancer tumorigenesis by transcriptionally activating PDGFA, which led to further Akt phosphorylation in breast cancer cells." (PMID 31253784, 2019). "We observed that the silencing of HMGA1 and FOXM1 reduced the ability of breast cancer cells-conditioned medium to promote the proliferation of ECs." (PMID 31311575, 2019). "Very recently we demonstrated that HMGA1 is involved in modulating breast cancer cells nuclear stiffness trough a mechanism involving histone H1 and that it drives also angiogenic properties acting in cooperation with forkhead box protein M1 (FOXM1)." (PMID 31382504, 2019). "The compounds bind directly to FOXM1 and alter its proteolytic sensitivity, reduce the cellular level of FOXM1 protein by a proteasome- dependent process, and suppress breast cancer cell proliferation and cell cycle progression and increase apoptosis." (PMID 31815181, 2019). "Here, we identify a new class of compounds effective in suppressing FOXM1 activity in breast cancers, and displaying good potency for antitumor efficacy." (PMID 31815181, 2019). "In breast cancer cells, gefitinib has been reported to reduce Forkhead Box M1 (FoxM1) levels through the activation of FoxO3a, that in turn results in inhibition of cyclin B, CDC25B and cell death." (PMID 30646603, 2019). "BBC and HGSC showed consistently increased FOXM1 mRNA and protein expression compared to other breast cancer molecular subtypes and normal breast tissue." (PMID 30795624, 2019). "From this catalogue, we selected a dataset of 818 breast cancer patients, and we found that FOXM1 was enriched in HMGA1 overexpressing patients, both at mRNA and protein levels." (PMID 31311575, 2019). "Firstly, we investigated the relationship between the combined expression of HMGA1 and FOXM1 with the VEGFA expression in breast cancer patients." (PMID 31311575, 2019). "Previous studies described an increased nuclear staining of FOXM1 in human mammary tumors vs. normal tissue and correlated the FOXM1 expression to Her2 expression, resistance to chemotherapy and a poor patient outcome." (PMID 31541075, 2019). "Given the evidence that FOXM1 coincides with metastasis of breast cancer, pancreatic cancer and prostate cancer, we next ectopically overexpressed FOXM1c in three oesophageal cancer cell lines, Eca109, KYSE180 and KYSE510." (PMID 30485581, 2019). "It has also been shown that in ER+ve breast cancer cells, tamoxinfen and fulvestrant treatment represses FOXM1 expression." (PMID 29180117, 2018). "The FOXM1 gene on human chromosome 12p13.33 is suggested to be amplified in 5.6% of breast cancer and 58% of malignant peripheral nerve sheath tumors and is frequently upregulated in human cancer." (PMID 30360388, 2018). "Consistently, ERβ1 has been shown to repress FOXM1 expression through targeting ERα to control cell proliferation in breast cancer." (PMID 29180117, 2018). "Park and colleagues reported that FoxM1 mediates Dox resistance in breast cancer by enhancing DNA repair." (PMID 29416660, 2018). "FOXM1 is one of the most commonly up-regulated transcripts in various cancers, including breast cancer." (PMID 30572639, 2018). "Our findings indeed confirm the clinical significance of FoxM1 in aggressive Middle Eastern breast cancer." (PMID 29707121, 2018). "In conclusion, the oncogenic transcription factor FoxM1 is overexpressed in breast cancer versus normal controls." (PMID 29416660, 2018).